BDNF (brain derived neurotrophic factor)
Diseases named in the same sentence as BDNF in open-access papers (continued):
Sharing a sentence is not in itself a finding about the gene and the disease.
epilepsy (230 papers, 2008 to 2026). A brain disorder characterized by episodes of abnormally increased neuronal discharge resulting in transient episodes of sensory or motor neurological dysfunction, or psychic dysfunction. "A higher expression of BDNF in the epileptic hippocampal specimens is also significantly associated with better outcomes of epilepsy surgery (p ≤ 0.01)." (PMID 39888294, 2025). "Extensive production of BDNF is linked with the development of epilepsy by inducing neuronal hyper-excitability; the BDNF serum level correlates with the severity of epileptic seizures." (PMID 41562905, 2025). "It has been shown that BDNF is highly expressed in brain regions that are implicated in the pathogenesis of epilepsy and epileptogenesis." (PMID 38006577, 2024). "The brain-derived neurotrophic factor (BDNF)–tropomyosin receptor kinase B (TrkB) pathway is closely associated with epilepsy." (PMID 38633914, 2024). "A systematic review demonstrated that BDNF/TrkB is overstated in epilepsy and associated with seizure severity." (PMID 38006577, 2024). "Lastly, while our research indicates a causal relationship between plasma BDNF levels and nITH, epilepsy, and focal epilepsy, it is worth noting that the MR analysis provides forecasting results without empirical verification." (PMID 38707431, 2024). "Conversely, polymorphism of BDNF in the Asian population is correlated with the incidence of epilepsy." (PMID 38006577, 2024). "Our study showed that a one SD increase in plasma BDNF levels was associated with a 7.3 % reduction in the risk of developing epilepsy." (PMID 38707431, 2024). "Our MR findings indicate that individuals genetically predisposed to higher plasma levels of BDNF are less likely to develop nITH, epilepsy, or focal epilepsy." (PMID 38707431, 2024). "Research has shown that the increase in vascular endothelial growth factor (VEGF) and decrease in brain-derived neurotrophic factor (BDNF) levels in the brain are linked to the development of epilepsy." (PMID 39650161, 2024). "Our study supports a possible causal relationship between elevated plasma BDNF levels and a reduced risk of nITH, epilepsy, and focal epilepsy." (PMID 38707431, 2024). "In the sensitivity analyses, the weighted median estimator revealed statistically significant evidence linking plasma BDNF levels (per SD increase) with decreased epilepsy risk (OR = 0.904; 95 % CI: 0.847–0.964, P = 0.002)." (PMID 38707431, 2024). "BDNF is increased or decreased in epilepsy, and depending on these findings, BDNF is implicated in epileptogenesis and epilepsy." (PMID 38006577, 2024). "FSDS mice exhibit several features that have been observed in mouse models of epilepsy including spontaneous seizures, increased susceptibility to induced seizures, astrocytosis, neuronal hypertrophy and upregulation of BDNF expression." (PMID 37199581, 2023). "In conclusion, the effect of nobiletin in epilepsy is associated with the apoptotic, BDNF-TrkB and PI3K/Akt signalling pathways." (PMID 37932838, 2023). "This study had a small sample size which affects the causal relationship between epilepsy and BDNF serum level." (PMID 37737447, 2023). "Reduced BDNF levels in the hippocampus and prefrontal cortex have been linked to aversive motivation, while increased BDNF levels are found in the mesolimbic system in conditions such as drug addiction, epilepsy, and neuropathic pain." (PMID 37997979, 2023). "A systematic review illustrated that BDNF/TrkB is exaggerated in epilepsy and linked with seizure severity." (PMID 37737447, 2023). "Dysregulation of RBFOX1 has been linked to intellectual disability, autism, epilepsy and Parkinson’s disease (PD) pathologies that are shared with dysregulation of brain-derived neurotrophic factor (BDNF) signaling." (PMID 38596700, 2022).
epilepsy (continued). "We used an adeno‐associated virus (AAV)‐mediated vector to supplement BDNF in the vlPAG area prior to the establishment of a pilocarpine‐nitroglycerin (Pilo‐NTG) combination‐induced comorbid model of epilepsy and migraine." (PMID 35557046, 2022). "It is suggested that BDNF reduces the CNS damage caused by epilepsy through its neurotrophic effect and then reveals the inhibitory effect on the epileptogenesis." (PMID 34899313, 2021). "Excessive BDNF significantly increases excitability of neurons and increases susceptibility to epilepsy, thus producing damage to neurons and possibly promoting epileptogenesis." (PMID 34899313, 2021). "BDNF is closely associated with the pathogenesis of epilepsy, and novel treatment methods that use BDNF can be developed." (PMID 35194435, 2021). "Cellular and molecular events underlying epilepsy can impair growth factor signaling in the brain and current evidence has associated BDNF with the pathophysiology of epilepsy in humans." (PMID 33584215, 2020). "As one of the CpG sites in adolescence was located in the gene BDNF, which is a key driver in neuronal growth and has been repeatedly linked to epilepsy, we expanded our search space to include all CpG sites annotated to BDNF (n = 73)." (PMID 31915053, 2020). "Carriers of at least one polymorphic BDNF rs6265 T allele tended to have a relatively higher epilepsy risk for children (OR = 1.53, 95% CI = 0.99–2.36; p = 0.054)." (PMID 33262686, 2020). "By comparing the two datasets (WP1066 + B and RX2 + B) we were able to decrease the dimensionality of the BDNF transcriptome into those most relevant by their association with epilepsy." (PMID 31455240, 2019). "Our new results suggest that sustained levels of BDNF at endogenous concentrations (0.7 nM) can dysregulate a major segment of the epilepsy-associated transcriptome." (PMID 31455240, 2019). "The results clearly show that WP + B (10 μM) and Ruxo (RX2 + B, 10 μM) block BDNF-induced changes in neuronal gene expression for epilepsy-linked genes and both appear to have a similar gene expression signature to that of DMSO+Water control." (PMID 31455240, 2019). "One girl aged 18 months (p.Arg255*, Val/Met BDNF polymorphism) had been diagnosed with epilepsy prior to the commencement of the study which was managed with Levitircetam, and two girls developed epilepsy during the intervention period and commenced Valproate." (PMID 29321033, 2018). "We have undertaken a study of variation in the NRSF and BDNF genes and its association with cognitive function in individuals with newly diagnosed epilepsy and with the change in cognitive function over the first year of treatment following diagnosis." (PMID 26708060, 2016). "In this study, we provide preliminary evidence to suggest that variants within the NRSF and BDNF genes influence cognitive function in adults with newly diagnosed epilepsy at both baseline and over the first year after diagnosis." (PMID 26708060, 2016). "In Finland, where fragile X chromosomes show a major haplotype, epilepsy was found to associate with polymorphisms in the gene for brain-derived neurotrophic factor in a subpopulation of FXS men." (PMID 27462212, 2016). "Our data support a trend towards association of polymorphic variants within the NRSF and BDNF genes and memory-related tasks in patients with a new diagnosis of epilepsy." (PMID 26708060, 2016). "Application of the neurotrophic factor BDNF abolished the increase in IGABA rundown associated with epilepsy." (PMID 23874269, 2013). "Several lines of evidence make the BDNF gene a plausible candidate gene for predisposition to epilepsy." (PMID 22654603, 2012). "Further, for the genotype frequencies of BDNF gene polymorphism, all two patient subgroups (idiopathic/symptomatic epilepsy), epileptic children with mental retardation and cerebral palsy showed similar distribution of the 270C/T allele." (PMID 22654603, 2012).
epilepsy (continued). "The modulation of synaptic transmission and plasticity by BDNF has been linked to changes in seizure activity and hyperexcitability, which may result in epilepsy." (PMID 40540445, 2025). "Second, BDNF may increase the risk of epilepsy through interfering with glutamatergic synaptic transmission and GABAergic inhibition in neurodegenerative diseases." (PMID 40564462, 2025). "In addition, overexpression of brain BDNF is linked with the development of epilepsy by inducing neuronal hyper-excitability; BDNF serum level is correlated with the severity of epileptic seizures." (PMID 40380033, 2025). "Additionally, Kir4.1 dysfunction is implicated in epilepsy pathophysiology; its inhibition increases brain-derived neurotrophic factor (BDNF) expression in astrocytes, potentially contributing to epileptogenesis and other neuropsychiatric disorders." (PMID 40001468, 2025). "Further preclinical studies indicated that the reduction of BDNF increases the risk of epilepsy." (PMID 38006577, 2024). "The brain-derived neurotrophic factor is a key factor in the induction and maintenance of synaptic plasticity and is also involved in the mechanisms underlying adaptive changes induced by epilepsy." (PMID 39408863, 2024). "Additionally, our study established a suggestive causal relationship between increased plasma BDNF levels and lower risks of epilepsy and focal epilepsy." (PMID 38707431, 2024). "These clinical findings indicated that an exaggerated BDNF level is associated with epilepsy." (PMID 38006577, 2024). "In a chronic rat epilepsy model, low serum BDNF levels have previously been linked with stress vulnerability and a predisposition to behavioral alterations that may recapitulate psychiatric comorbidities in patients." (PMID 36941269, 2023). "One study found that the Val66Met polymorphism in the brain-derived neurotrophic factor (BDNF) gene may lessen the epilepsy phenotype in FXS patients, as this polymorphism can affect cerebral anatomy and fragile X-associated neuropsychiatric disorders (FXAND)." (PMID 37420260, 2023). "Our results are generally in agreement with those published so far, showing that BDNF could indeed be an informative biomarker reflecting epilepsy-associated neural tissue reorganization." (PMID 37539386, 2023). "The hypothesis suggested that the expression of BDNF can suppress epileptogenesis by a combined receptor-ligand pathway; and the TrkB binding to BDNF may be the most closely associated with epilepsy between its two corresponding receptor-ligand pathways." (PMID 34899313, 2021). "In addition, decreased percentage of BDNF alleles in KA-induced epilepsy model of rats causes stronger mossy fiber sprouting to lead to the formation of abnormal excitatory circuits in the brain, which are thought to be associated with the epileptogenesis." (PMID 34899313, 2021). "This differential expression pattern for each epilepsy-associated molecule suggested that the anti-epileptic mechanism of SVHRP may undergo the BDNF-NPY pathway." (PMID 33825777, 2021). "Thus, this mini-review focuses on updating the new evidence of the role of BDNF in epileptogenesis and discussing the possibility of BDNF as an underlying target for the treatment of epilepsy." (PMID 34899313, 2021). "BDNF, essential in the regulation of neuronal survival and differentiation, synaptic transmission, and plasticity, plays a pivotal role in the pathogenesis of epilepsy and central comorbid conditions associated with epilepsy." (PMID 33262686, 2020). "Several studies have investigated the association between BDNF gene variation and epilepsy." (PMID 33262686, 2020). "Continuous exposure to BDNF alters the expression of 194 epilepsy-linked genes identified by IPA." (PMID 31455240, 2019).
epilepsy (continued). "In this respect, epilepsy is an exception as it is associated with increased levels of BDNF." (PMID 30117106, 2019). "Besides epilepsy and DDs, BDNF is also implicated in the pathogenesis of pain and neurodegenerative disorders." (PMID 30356026, 2018). "BDNF and its receptors have been implicated in the development of epilepsy." (PMID 30914877, 2018). "All these evidences illustrate a causal role of BDNF in the development of epilepsy." (PMID 29358904, 2017). "The present results demonstrated for the first time that inhibition of Kir4.1 channels facilitates the expression of BDNF in astrocytes, which may be linked to the development of epilepsy and other neuropsychiatric disorders." (PMID 29358904, 2017). "According to the results of EEG and behavior analyses, the up-regulation of BDNF by miR-155 antagonist was associated with the amelioration of seizures, representing a paradox considering the formerly reported expression pattern of BDNF in epilepsy." (PMID 27303295, 2016). "Moreover, our data also evidently showed that blocking or overexpression of miR-155 altered the production of BDNF, representing a close association between the two indicators in the onset of epilepsy." (PMID 27303295, 2016). "BDNF-TrkB signaling is implicated in experimental seizures and epilepsy." (PMID 27273072, 2016). "Variations in the BDNF gene might alter function and neurotrophic effects of the BDNF protein, thus ultimately predisposing individuals to the development of epilepsy." (PMID 22654603, 2012). "We have previously reported that local, intrahippocampal supplementation of fibroblast growth factor-2 (FGF-2) and brain-derived neurotrophic factor (BDNF) increases neurogenesis, reduces neuronal loss, and reduces the occurrence of spontaneous seizures in a model of damage-associated epilepsy." (PMID 21087489, 2010). "However, increasing BDNF levels may play a contrasting effect by increasing neuronal excitability, neuronal injury and predisposes for the development of epilepsy." (PMID 38006577, 2024). "In epilepsy, the activation of GluN2A-containing NMDARs is necessary for epileptogenesis, and GluN2A activates a distinct intracellular signaling pathway that is linked to brain-derived neurotrophic factor (BDNF) expression and then contributes to the development of epilepsy." (PMID 35513389, 2022). "A recent investigation from Hong Kong and Malaysia for BDNF genotyping showed a significant correlation between BDNF and risk of symptomatic epilepsy in Malaysian Indians, suggesting that BDNF polymorphisms may increase the incidence of epilepsy in Malaysian Indians." (PMID 34899313, 2021). "Thus, all these studies support the idea that high expression of BDNF in certain brain regions may cause epilepsy." (PMID 34899313, 2021). "In addition to the 194 epilepsy-associated genes, pathway analysis suggests that increased levels of BDNF alters the expression of essential neurobiological gene sets that are required for brain development and that are dysregulated during epileptogenesis in animal models and human patients." (PMID 31455240, 2019). "Visual stimulation reduces epilepsy susceptibility in neonatal HBIN rats, likely through upregulation of BDNF and SYN expression in the occipital cortex." (PMID 40589985, 2025). "Among the trophic factors investigated, BDNF appears to play a particularly complex and dualistic role in epilepsy." (PMID 41516142, 2025). "Our research indicates a significant decline in BDNF concentrations within the cognitively impaired group compared to those who are cognitively unimpaired among adult individuals with epilepsy (PWE)." (PMID 40291844, 2025).
epilepsy (continued). "Brain-derived neurotrophic factor (BDNF), a crucial regulator of neuronal survival and plasticity, exhibits a robust circadian regulation that is disrupted during epilepsy." (PMID 40940742, 2025). "This was an expected observation since several studies have already demonstrated the link between BDNF and epilepsy." (PMID 40177581, 2025). "Clinical studies showed controversial correlations of BDNF levels and epileptogenesis, confounded by the various subtypes of epilepsy and anti‐seizure medication." (PMID 40193544, 2025). "Follow-up showed tDCS reduced adverse outcomes such as mossy fiber sprouting and BDNF overexpression, highlighting its therapeutic potential for epilepsy." (PMID 40895116, 2025). "Previous research indicates that the BDNF/TrkB pathway helps prevent or suppress epilepsy in brain injury models, which is consistent with the lower epileptic susceptibility observed in the NH-V group." (PMID 40589985, 2025). "In epilepsy models, the brain-derived neurotrophic factor (BDNF) pathway positively regulates NAT10 expression." (PMID 41446042, 2025). "On the contrary, a recent Indian clinical study on 74 adult (18–50 age) persons with epilepsy showed that there is a different relationship between MoCA scores and the level of BDNF." (PMID 41562905, 2025). "In epilepsy models, circadian BDNF regulation is lost, potentially contributing to the neuronal hyperexcitability and impaired plasticity observed in epilepsy." (PMID 40940742, 2025). "In the PTZ-induced epilepsy model, the upregulation of BDNF suggests its role in the enhancement of glutamatergic response and hindering GABAergic neurotransmission." (PMID 39776284, 2025). "This is in accordance with the results showing a rapid upregulation in BDNF under the same conditions, and with the effect of a peptide that uncouples TrkB from PLCγ1 which prevents epilepsy induced by status epilepticus after kainate infusion in the amygdala." (PMID 40890771, 2025). "Of interest, BDNF promotes oxidative stress and mitochondrial dysfunction which trigger the development and progression of epilepsy." (PMID 38006577, 2024). "The autophagy/BDNF pathway is an essential pathway to maintain neuronal integrity and attenuate epileptogenesis and the development of epilepsy." (PMID 38006577, 2024). "A case-control study on 80 patients with epilepsy and 13 healthy controls revealed that BDNF serum levels were higher in epileptic patients as compared to controls." (PMID 38006577, 2024). "The combined analysis of three consortium datasets demonstrated a considerable impact of plasma BDNF on epilepsy (OR = 0.94, 95 % CI: 0.90–0.98, P < 0.01) and a suggestive impact on focal epilepsy (OR = 0.94, 95 % CI: 0.89–0.99, P = 0.02)." (PMID 38707431, 2024). "BDNF improves GABAergic neurotransmission in rats with experimental epilepsy through the phosphorylation of different subunits." (PMID 38006577, 2024). "The role of BDNF in reducing epilepsy-induced CNS damage is attributed to its neurotrophic properties and subsequent inhibitory effects on epileptogenesis." (PMID 38707431, 2024). "Of interest, pro-BDNF release and p75NT expression are augmented in experimental epilepsy due to the inhibition of machinery cleavage of pro-BDNF to BDNF." (PMID 38006577, 2024). "A recent clinical study revealed that serum BDNF levels are significantly increased in patients with epilepsy who have received PRM or valproate treatment." (PMID 39727966, 2024). "BDNF has a neuroprotective effect and inhibits epileptogenesis thereby reducing epilepsy induced neuronal injury in rats." (PMID 38006577, 2024). "The present review highlighted that BDNF has detrimental and protective effects in relation to the development of epileptogenesis and the progression of epilepsy." (PMID 38006577, 2024).